NGF (nerve growth factor)
Diseases named in the same sentence as NGF in open-access papers (continued):
Sharing a sentence is not in itself a finding about the gene and the disease.
tumor (continued). "The blockage of NGF/Trk signaling with pan-Trk inhibitor PLX-7486 or the ablation of Tuft cells (a local source of ACh which stimulates cancer cells to produce NGF) within GC abrogates tumor development and decreases proliferation and tumorigenesis." (PMID 30741921, 2019). "On the contrary, NGF exerts a dual role by activating immune responses following acute insult, while concomitantly avoiding tumor growth sustained by chronic inflammation via a timely resolution of the immune response." (PMID 31812953, 2019). "MM and MGUS patient serum was tested for NGF protein, and a statistically significant correlation was found between paraprotein levels (as a marker for tumour load) and serum NGF." (PMID 31578352, 2019). "Main findings on the role of neurotrophin NGF and its receptors TrkA and p75NTR in tumor surveillance by innate and adaptive immune cells." (PMID 31812953, 2019). "NGF has been reported to be involved in tumor growth and invasion, by promoting cell proliferation and survival." (PMID 31515263, 2019). "Of note, Rho GTPase-mediated recruitment of CD44 to the cell membrane by NGF-TrkA further contributes to CSCs stemness maintenance and survival, resulting in higher tumor aggressiveness." (PMID 31812953, 2019). "In particular, given the Tregs and PD1 control by p75NTR and NGF, NGF pathway inhibition would result in immune tolerance induction, thus challenging the use tout-court of TrkA inhibitors to dampen tumor growth." (PMID 31812953, 2019). "Nonetheless, increasing evidences pinpoint the involvement of neurotrophins, and specially NGF, in tumor immune surveillance through cytokines-driven modulation of the innate and acquired immune system cells." (PMID 31812953, 2019). "NGF/TrkA signaling and cholinergic innervation of the tumor niche take central stage in tumor initiation and progression, as well as metastatic spreading." (PMID 31812953, 2019). "We have used in vivo murine models of MM to show significant induction of nerve growth factor (NGF) by the tumour-bearing bone microenvironment, alongside other known pain-related characteristics such as spinal glial cell activation and reduced locomotion." (PMID 31578352, 2019). "CSCs respond to NGF by TrkA-mediated autocrine proliferation and neurotransmitter release leading to axonal growth around the tumors, tumor expansion and long distance CSCs spreading through the nerves." (PMID 31812953, 2019). "The neurotrophic tyrosine kinase receptor TrkA (NTRK1) and its ligand nerve growth factor (NGF) are emerging promoters of tumor progression." (PMID 29802376, 2018). "Extracellular release of neurotrophic factors [e.g. nerve growth factor (NGF)] by tumor cells can contribute to cancer progression." (PMID 30327461, 2018). "TrkA-expressing tumor cells in the presence of NGF undergo neuronal differentiation, while NGF deprivation leads to apoptosis." (PMID 30034627, 2018). "NGF is produced in sufficient amounts in normal oral epithelium and in tumor cells of HNSCC, including cultured cell lines." (PMID 29904026, 2018). "The treatment of tumor-bearing mice with NGF resulted in a reduction of tumor volume by 72%, increased lymphocytic infiltration of the tumor tissue, elevated levels of serum IL-1β and TNF-α and an increase in the activities of both SDH and LDH in EAC cells." (PMID 28878143, 2017). "The GNC–siRNA group induced the most significant inhibition on the expression level of both NGF mRNA and NGF protein in the PDX tumours." (PMID 28440296, 2017). "KIF1Bβ is a haploinsufficient 1p36 tumor suppressor and a downstream target of EglN3, which was found necessary and sufficient to mediate Nerve Growth Factor (NGF) withdrawal-induced apoptosis during neural crest development." (PMID 29203804, 2017). "Application of NGF alone or in combination with other drugs contributed to the vascularization of tumor nodes, the germination of muscle fibers and the proliferation of connective tissue." (PMID 28878143, 2017).
tumor (continued). "We evaluated the GNC–siRNA complex in depleting the expression level of NGF mRNA and NGF protein in tumours." (PMID 28440296, 2017). "When administered alone, CVF had an in vivo antitumor effect comparable to that of NGF (column three) which resulted at day 12 in a reduction of mean tumor size by 68% compared to the control." (PMID 28878143, 2017). "Tumour-associated factors, like CGRP, can trigger the promotion of pathological sprouting of sensory neurons by increasing NGF expression." (PMID 28845385, 2017). "Large blood vessels among nodes of tumor cells were typical for the experimental group in which animals received NGF only." (PMID 28878143, 2017). "NGF caused a considerable increase in the level of TNF-α and IL-1β in the serum of the tumor-bearing mice." (PMID 28878143, 2017). "GNC–siRNA group significantly reduced the NGF mRNA expression in orthotopic tumours compared to the saline control." (PMID 28440296, 2017). "GNC–siRNA-#2 and GNC–siRNA-#5 complexes showed more effective antitumour effects and NGF gene knockdown effects than GNC–siRNA-#3 in the orthotopic tumours." (PMID 28440296, 2017). "The GNC–siRNA complex provides the NGF siRNA not only a protective structure against the harsh biological environment but also an opportunity for passive targeting to the tumour tissues." (PMID 28440296, 2017). "Treatment of tumor-bearing mice with NGF led to an increase in the activity of both LDH and SDH (5.9% and 7.4%, respectively, p < 0.05), i.e., both anaerobic and aerobic oxidation were increased under NGF treatment." (PMID 28878143, 2017). "In the present paper, we demonstrate that treatment of mice by NGF leads to increased lymphocyte infiltration of the tumor." (PMID 28878143, 2017). "Communication between neurons and tumour sites utilise neuropeptides (e.g. nerve growth factor (NGF)) to support those key pathological events (angiogenesis and metastasis) that are key for cancer progression." (PMID 29100335, 2017). "In the in vivo models, GNC–siRNA complex enhanced the blood circulation and the accumulation of NGF siRNA to tumour sites, induced significant NGF silencing." (PMID 28440296, 2017). "In a variety of human cancers, NGF has been shown to play a key role in tumor cell growth, proliferation, invasion, angiogenesis, and so on." (PMID 27835587, 2016). "The question about NGF role in tumor induction/progression has been investigated in different in vivo and in vitro experimental approaches." (PMID 27439311, 2016). "The model confirms the experimental observations that a tumour is able to promote nerve formation/elongation around itself, and that high levels of nerve growth factor and axon guidance molecules are recorded in the presence of a tumour." (PMID 26861829, 2016). "Particularly, several in vitro experiments have shown that NGF is capable of retarding growth and inducing persistent differentiation of neurogenic tumor cell lines." (PMID 27439311, 2016). "The addition of NGF (100 ng/ml) plus TRAIL (200 ng/ml) to soft agar abrogated tumour spheroid growth by TrkA SH-SY5Y cells, resulting in a mean (±S.D)." (PMID 27551499, 2016). "Over the last three decades, a consistent number of published studies have shown that NGF can promote cell differentiation and arrest tumor progression, as observed in primary and cell line tumor cells." (PMID 27439311, 2016). "Based on our long-lasting experience in the physiopathology of NGF, we aimed to review previous and recent in vivo and in vitro NGF studies on tumor cell induction, progression and arrest." (PMID 27439311, 2016). "As shown, PC-12 tumor cells proliferate under baseline conditions and start to differentiate and produce neuritis after NGF exposure over few consecutive days." (PMID 27439311, 2016). "Since tumour growth is enhanced by NGF, we assume that the growth rate of Tp is increased in a saturating manner by this factor." (PMID 26861829, 2016).
tumor (continued). "NGF (100 ng/ml) added to soft agar significantly reduced the number of tumour spheroids formed by TrkA SH-SY5Y cells by a mean (±S.D)." (PMID 27551499, 2016). "As the NGF-TrkA signaling is classically implicated in MAPK and AKT activation and TrkA overexpression stimulates both cascades in other tumor cells, we first verified that the two pathways are also activated downstream to NGF-TrkA signaling in MM cells." (PMID 26496938, 2015). "This event determinate an evident decrease in the number of PC12 tumor cells, presumably related to the NGF-induced neural differentiation." (PMID 25976344, 2015). "Accumulating evidence indicates that neuronal system-dependent facilitation of tumor angiogenesis and tumor growth by calcitonin gene-related peptide or nerve growth factor occurred in breast cancer." (PMID 24996968, 2014). "In overall, cvNGF shows the anti-tumor and weight-increasing effects which are opposite to those described for mammalian NGF (mNGF)." (PMID 24577582, 2014). "Conversely, both PAI-1, which is used as a prognostic marker for cancer, and NGF can induce tumor angiogenesis." (PMID 23825664, 2013). "The release of NGF by cancer cells and the NGF-induced sensitisation of primary afferent nerves in the tumour-laden bone highlight potential mechanisms for pain relief with anti-NGF antibodies." (PMID 23500200, 2013). "The expression of NGF and HO1 was seen mainly in the cytoplasm of tumor cells, and the expression of NGF and HO1 was grouped positive in 31% (45/145 of cases) and 49% (71/145) of BRCA samples, respectively." (PMID 24180625, 2013). "Blocking of NGF with anti-NGF antibodies or small interfering RNA against NGF inhibited tumor growth and metastasis and inhibitors for TrkA or p75NTR, downstream signaling targets of NGF, also had pro-apoptotic and anti-proliferative effects on BRCA cells." (PMID 24180625, 2013). "When considering the tumor-progressing role of NGF, there is a possibility that HO1 is also involved in the progression of cancers." (PMID 24180625, 2013). "High levels of NGF have been detected in many different tumor types and can be targeted to inhibit the tumor cell proliferation, angiogenesis, and metastasis." (PMID 23637956, 2013). "In tumor with later metastasis, let-7e targets nerve growth factor (NGF), whose deprivation was supposed to induce apoptosis." (PMID 23282077, 2012). "Consistently, cell cycle inhibition mot only promotes the death of naive PC12 (pheochromocytoma) tumor cells, but also prevents the death of nerve growth factor- (NGF-) differentiated PC12 neuronal cells." (PMID 22547985, 2012). "We observe indeed that, after 1 h treatment, while NGF activates the expression of a mitotic and anti-apoptotic outcome mRNAs, proNGFs activates pro-apoptotic genes, including tumour suppressor mRNAs." (PMID 21677785, 2011). "NGF was significantly downregulated in tumor-bearing mice but the changes were less extensive than the changes in transmitter expression." (PMID 21637823, 2011). "The NGF produced by target tissues or tumor cells activates TrkA receptors expressed on the terminals of C-fibers presumably including those innervating the skeleton." (PMID 21138586, 2010). "The expression of NGF and its receptors in a wide range of tumor cells show its critical relationship with tumor proliferation and invasion, especially in nerve tissue." (PMID 20219134, 2010). "PHD3 overexpression mediated tumour cell growth and invasion by induction of apoptosis in a nerve growth factor-dependent manner by the activation of caspase-3 and phosphorylation of focal adhesion kinase HIF-1 independently." (PMID 20978507, 2010). "Inhibition of NGF with neutralizing antibodies, or small interfering RNA, strongly reduces angiogenesis and tumor development in immunodeficient mice." (PMID 20569463, 2010). "Tumour cells expressing TrkA undergo cell differentiation in the presence of NGF, while withdrawal of NGF induces apoptosis." (PMID 20003389, 2009).
tumor (continued). "We also showed that the ectopic production of nerve growth factor (NGF) in the melanoma tumor tissue as a tumor-released mediator can induce expression of the TF Egr-1 in the salivary gland." (PMID 19517020, 2009). "In NBs, the amount of NGF in the tumour microenvironment and expression of TrkA receptor has a profound effect on cellular behaviour." (PMID 20003389, 2009). "The positive cell number of CXCL12, CXCR4, MMP-2, MMP-9 and NGF expression of tumor cells in CXCL12-treated group was the highest." (PMID 18983683, 2008). "On the contrary, as our results, most of previous reports regarding other cancers have shown the positive relationship between malignant potential of tumours and expression of NGF or its receptors." (PMID 16832412, 2006). "Nerve growth factor mRNA expression was higher in the tumour portion than the normal epithelium portion in 89% (17 of 19) of the patients, and TrkA mRNA expression level was higher in the tumour portion in 84% (16 of 19) of the patients." (PMID 16832412, 2006). "Other biological and genetic factors such as low telomerase activity, low expression of nerve growth factor and its receptor Trk-A, tumour diploidy and gain of chromosome 17q material have been associated with poor outcome in NB." (PMID 12888814, 2003). "Tumor cells overproduce neurotrophic factors (such as NGF and BDNF) and axon guidance molecules (like Netrin‐1), which attract nerve fibers into the tumor and may promote new nerve formation." (PMID 41583906, 2026). "Results suggested that over-expression of NGF could reverse the tumor-suppressive effect of ZNF662 in TNBC cells." (PMID 40612670, 2025). "In summary, our results indicated that ZNF662 may act as a tumor suppressor gene in TNBC by reducing the expression of NGF." (PMID 40612670, 2025). "The integration of neural components into organoid models to dissect tumor–nerve crosstalk and screen therapies targeting neurotrophic factors (e.g., NGF, BDNF) or glutamate receptors (α-Amino-3-Hydroxy-5-Methyl-4-Isoxazole Propionic Acid (AMPA)/N-Methyl-D-Aspartate (NMDA)) is crucial." (PMID 40243726, 2025). "Reducing the supply of serine or inhibiting NGF may be an attractive strategy for slowing the progress of neuroinvasion (NI) and tumor growth." (PMID 40427098, 2025). "Together with TRKA-dependent induction of IL-10 in human macrophages exposed to tumor-derived danger signals, these data support a model in which NGF promotes immune suppressive myeloid states that hinder cytotoxic lymphocyte activity within mineralized tumor beds." (PMID 41567220, 2025). "NGF may affect the immune microenvironment of the tumour by regulating the function of immune cells, such as macrophages and T cells." (PMID 40860871, 2025). "Because nociceptor–tumor signaling intersects with neurotrophin biology, prospective capture of pain and neurosensory parameters is warranted, while monitoring for joint events if anti-NGF strategies are explored." (PMID 41567220, 2025). "Activation of NGF/TrkA signaling therefore induces tumor progression and either the NGF or TrkA may be a therapeutic target against PDAC." (PMID 40806192, 2025). "Molecular profiling of tumor tissue or exosomes for neurotrophic factors (NGF, BDNF, GDNF), chemokines (CXCL12, CCL2), or neuronal transcription factors (POU4F1) may serve as predictive biomarkers of neural involvement." (PMID 41009819, 2025). "T−cell sources of NGF have been described, indicating that adaptive lymphocytes can both sense and supply neurotrophin signals that influence retention and function within the tumor bed." (PMID 41383615, 2025). "Neurotrophin–immune crosstalk is further supported by studies showing that NGF–TrkA signaling regulates leukocyte adhesion and trafficking programs and that nociceptive pathways—and their neurotrophin ligands—shape the inflammatory tone of the tumor bed." (PMID 41567220, 2025).
tumor (continued). "Remarkably, this process reflects the neurotrophic recruitment by cancer cells: serine deprivation induces ribosomal stalling specifically at two of the six serine codons (TCC and TCT), thereby driving PDAC cells to selectively translate and secrete NGF, promoting tumor innervation." (PMID 40861469, 2025). "Given its central role in tumor–nerve interactions, NGF is a promising therapeutic target." (PMID 41009819, 2025). "In in vivo xenograft mouse models, NGF overexpression enhanced tumor growth." (PMID 41301953, 2025). "The NGF is also broadly expressed by tumor cells, inflammatory cells and immune cells." (PMID 40806192, 2025). "In OS, NGF-TrkA signaling is suspected to enhance angiogenesis by influencing endothelial and tumor cells, although the molecular mechanisms remain unclear." (PMID 39860039, 2025). "During axonogenesis, neurotrophins, such as the nerve growth factor (NGF) and brain-derived neurotrophic factor (BDNF), semaphorins (axonal guidance molecules), and ephrinB1-containing exosomes secreted by tumor cells drive neuron morphogenesis causing a local increase in nerve density." (PMID 41306965, 2025). "Relies on anatomical proximity; tumor cells interact with the neural microenvironment via neurotrophic factors (e.g., NGF).May involve indirect spread through perineural lymphatic or vascular channels but primarily extends locally along nerve pathways." (PMID 40421086, 2025). "Since NGF is also secreted by blood cells and nerve cells that form the tumor microenvironment, it has been suggested that NGF may influence the sensitivity of GBM cells to chemotherapy and thus the survival of patients." (PMID 40426873, 2025). "On the other hand, NGF may also exert anti-tumour effects by inducing apoptosis or inhibiting angiogenesis in tumour cells." (PMID 40860871, 2025). "The sprouting in the periosteum may be in response to tumor derived factors like NGF released by cells in the tumor–bone microenvironment." (PMID 41228327, 2025). "Experimental studies have shown that PNI in PDAC is an active process involving reciprocal tumour–nerve signalling via neurotrophic factors (e.g., NGF, GDNF, CXCL12), extracellular matrix remodelling, and Schwann cell activation, which together create a permissive niche for perineural invasion." (PMID 41227159, 2025). "The NGF receptor is also expressed in transgenic tumor cells, suggesting that Tax may activate an autocrine mechanism through the upregulation of NGF." (PMID 41153438, 2025). "SCs can be activated by tumour-secreted proteins, e.g., TNFα, which is characterized by the upregulation of activation markers (e.g., c-Jun, glial fibrillary acidic protein, and p75NTR) and the cascade expression of NGF and TNFα." (PMID 40783715, 2025). "The first reports the results of a preclinical study evaluating whether the early or late administration of an NGF-sequestering antibody (mAb 911) could attenuate tumor-induced nerve sprouting, neuroma formation, and subsequent cancer pain." (PMID 41301953, 2025). "NGF initiates the expansion of sensory afferent and autonomic efferent nerve fibres around the tumour by stimulating axonal growth, thereby further enhancing the interaction between nerves and tumours." (PMID 40579785, 2025). "This indicates that if NGF reduction reduced malignant cell proliferation, then inhibiting NGF may provide improved outcomes in inhibiting tumor growth." (PMID 40563551, 2025). "Similarly, within tumor, Schwann cells dedifferentiate into an amyelin phenotype when subjected to biochemical signals and start to release neurotrophines like NGF, GDNF, BDNF stimulating neuronal growth." (PMID 39723256, 2024). "Tumor cells and the inflammatory response release nerve growth factor (NGF), which promotes pathological sprouting of the sensory nerves leading to a 10- to 70-fold increase in the density of the nerve fibers and the formation of neuroma-like structures within them." (PMID 39202730, 2024).